CHEK2 (checkpoint kinase 2)
Diseases named in the same sentence as CHEK2 in open-access papers (continued):
Sharing a sentence is not in itself a finding about the gene and the disease.
lung carcinoma (52 papers, 2012 to 2025). "CHEK2 gene mutation is also a pathogenic mutation in lung cancer and increases susceptibility to lung cancer." (PMID 35300428, 2022). "Previous studies have shown that two rare variants, rs11571833 in BRCA2 and rs17879961 in CHEK2 were associated with lung cancer." (PMID 27632928, 2016). "Recently, an imputation study identified two rare variants rs11571833 in BRCA2 and rs17879961 in CHEK2 were associated with lung cancer." (PMID 27632928, 2016). "The CHEK2 Ile157Thr germline mutation has been linked to an increased risk of breast, colon, kidney, prostate, and thyroid cancers, but its association with lung cancer is less pronounced." (PMID 41015991, 2025). "Furthermore, the fact that the variant was found in families with history of prostate, breast, gastric, and lung cancer supports CHEK2 as a multiorgan cancer susceptibility gene, as previously suggested." (PMID 33158149, 2020). "Overall, 1267 lung cancer cases were retrieved from TCGA which revealed a higher relative prevalence of EGFR (n = 30, 22.9% vs n = 148, 11.7%, P = 0.001) and CHEK2 (n = 11, 8.4% vs n = 20, 1.6%, P = 0.000001) mutations in the Northern England population." (PMID 37702806, 2023). "Two patients (one lung cancer and one stomach cancer) were treated with a CHEK2-targeted PARP-inhibitor: one patient had a stable disease followed by rapid progression, and one patient experienced progressive disease at first tumor evaluation." (PMID 35323355, 2022). "Surprisingly, a great number of CHEK2 alterations were found (10% of exploitable samples), being the most frequent actionable molecular alteration found mostly in lung cancer." (PMID 35323355, 2022). "Studies have shown that checkpoint kinase 2 (CHEK2) has a critical role in repairing DNA damage, and that CHEK2 overexpression is closely related to the occurrence of lung cancer." (PMID 33988228, 2021). "Examples of where commercial reports might significantly differ from either the national trial finder or the opinion of the PROSPECT-NE MTB are highlighted by the CHEK2 abnormalities in 8 patients with lung cancer." (PMID 37702806, 2023). "In addition, the correlation between KLC4 and CHEK1, CHEK2 was investigated in both lung cancer and cervical cancer using RNA-sequencing data from publicly available microarray datasets." (PMID 32457423, 2020). "Interestingly, two different investigators have reported that the CHEK2 I157Tmutation seems to be protective against lung cancer in patients from Eastern Europe." (PMID 28680382, 2017). "Another CHEK2 VUS was detected in several of our patients with family histories of breast, prostate, pancreatic, or lung cancer." (PMID 41294693, 2025).
thyroid cancer (48 papers, 2006 to 2025). "A 2021 study found a pathogenic variant of the CHEK2 founder in Portuguese Roma as a likely basis of thyroid cancer and other tumor manifestations in the Roma population." (PMID 40724130, 2025). "While the clinical significance of the p.Thr519Met variant remains inconclusive, prior studies have implicated other CHEK2 mutations in the pathogenesis of breast, colorectal, and thyroid cancers." (PMID 40688847, 2025). "Germline pathogenic and likely pathogenic (P/LPs) variants in CHEK2 increase an individual’s risk of breast, colorectal, kidney, prostate, and thyroid cancer." (PMID 39594831, 2024). "CHEK2 germline loss-of-function variants have been reported in certain pediatric cancer patient cohorts, including neuroblastomas, non-Hodgkin lymphomas, thyroid cancer, melanomas, sarcomas, and brain tumors." (PMID 36980535, 2023). "In a study on the association of CHEK2 mutations with different cancer types in Poland, the most significant correlation was observed between thyroid cancer (mainly PTC) and CHEK2 protein-truncating mutations." (PMID 35626065, 2022). "The incidence of thyroid cancer was slightly higher in the group of CHEK2 c.1100delC mutation carriers (5/670 (0,9%) vs 99/86303 (0,1%))." (PMID 35101071, 2022). "The risk of thyroid cancer in women with a (truncating or missense) mutation in CHEK2 is approximately nine times that of the general population of Poland." (PMID 35205705, 2022). "Patients with thyroid cancer had a significantly higher prevalence of truncating CHEK2 mutations (IVS2 + 1G > A, c.1100delC or del 5395) than the control group (OR 5,7; p = 0,006)." (PMID 35101071, 2022). "The age-adjusted hazard ratio for developing thyroid cancer was 1.89 (0.46–7.79; p = 0.38) for those with a CHEK2 protein-truncating mutation and 2.75 (1.29–5.85; p = 0.009) for those with a CHEK2 missense mutation." (PMID 35205705, 2022). "The age-adjusted hazard ratio for developing thyroid cancer was 1.89 (0.46–7.79; p = 0.38) for those with a CHEK2 protein-truncating mutation and was 2.75 (1.29–5.85; p = 0.009) for those with a CHEK2 missense mutation." (PMID 35205705, 2022). "Among the 914 women with a CHEK2 mutation, there were 10 thyroid cancers observed, versus 1.04 expected (SIR = 8.7)." (PMID 35205705, 2022). "There is possibly an elevated risk of thyroid cancers in CHEK2 c.444 + 1G > A carriers, although the number of carriers in these studies was limited." (PMID 35101071, 2022). "The CHEK2 missense p.I157T (c.470T>C) germline mutation, which was previously reported to increase the risk of breast, colon, kidney, prostate, and thyroid cancers, is also associated with adult granulosa cell tumors (AGCTs)." (PMID 35267514, 2022). "In our cohort, the most significant predictor of thyroid cancer was the presence of a CHEK2 mutation." (PMID 35205705, 2022). "We have previously estimated that a CHEK2 mutation increases the risk of thyroid cancer by 3.3 times over the general population." (PMID 35205705, 2022). "The CHEK2 variants found also led to additional screening for breast, prostate, kidney, and thyroid cancers where appropriate." (PMID 35128723, 2022). "Current evidence suggests a low absolute risk of thyroid cancer in CHEK2 mutation carriers, and these are mostly of differentiated, non-medullary histology." (PMID 35101071, 2022). "Among the women with a BRCA1 mutation there was only one case of thyroid cancer observed; however, this woman also carried a CHEK2 mutation." (PMID 35205705, 2022). "In our study, 10 of 914 CHEK2 mutation carriers developed thyroid cancer (HR = 2.52; 95% 1.27–5.01; p = 0.009)." (PMID 35205705, 2022). "Six studies compared the prevalence of germline CHEK2 mutations in patients with thyroid cancer with a matched cohort." (PMID 35101071, 2022). "One small study examined the use of ultrasound screening for thyroid cancer in 62 female carriers of CHEK2 truncating mutations (c.1100delC, IVS2 + 1G > A, del5395)." (PMID 35101071, 2022).
thyroid cancer (continued). "Polymorphisms and mutations in the CHEK2 gene can lead to occurrence of sporadic cancers; however, they also cause predisposition to familial types of cancer, including thyroid cancer." (PMID 33530461, 2021). "Examples of such mutations are CHEK2 gene mutations, causing breast, kidney, gastric, colorectal, prostate, lung, ovarian, and thyroid cancers." (PMID 32570972, 2020). "There is also a reported association between CHEK2 and other cancers, including male breast, kidney, gastric, colorectal, prostate, lung, ovarian, and thyroid cancers." (PMID 32570972, 2020). "A woman presenting with mutation of CHEK2 gene has a high risk of suffering breast and thyroid carcinomas." (PMID 32571290, 2020). "CHEK2 mutations, which occur in various sporadic cancers, predispose individuals to several types of hereditary malignancy, including thyroid cancer." (PMID 31703344, 2019). "Four of the five patients from group U with a truncating CHEK2 mutation had thyroid cancer, pointing to a broader tumor spectrum in patients with pathogenic CHEK2 variants." (PMID 30680046, 2019). "We demonstrated that in the Great Poland population the c.470C CHEK2 variant increases the risk of developing differentiated thyroid cancer almost twice (OR = 1.81, p = 0.004)." (PMID 25798211, 2015). "Population screening for this CHEK2 gene variant should be considered to be an effective strategy for differentiated thyroid carcinoma early detection and control." (PMID 25798211, 2015). "There have been reports on the increased risk for thyroid cancers with CHEK2 mutations." (PMID 39860595, 2025). "Mutations in CHEK2, particularly those that result in loss of function, compromise these key cellular functions, leading to an increased susceptibility to the development of malignancies, including thyroid cancer." (PMID 39860595, 2025). "In the group of 919 CHEK2 mutation carriers, 10 patients developed thyroid cancer (SIR 9.6)." (PMID 37434214, 2023). "Overall, 10 of the 53 cases of second primary thyroid cancer (19%) could be attributed to carrying a CHEK2 mutation." (PMID 35205705, 2022). "Hence, we reviewed the literature to explore the possible association between a CHEK2 mutation and thyroid cancer." (PMID 35101071, 2022). "Should we screen carriers of a CHEK2 c.1100delC or other truncating variants for thyroid cancer?" (PMID 35101071, 2022). "The annual risk of thyroid cancer was 114 per 100,000 per year in those with a CHEK2 mutation." (PMID 35205705, 2022). "Maybe a different environmental or genetic factor could be responsible for the stronger association between CHEK2 variants and thyroid cancer in the Polish population." (PMID 35101071, 2022). "CHEK2 mutations are associated with cancers of the thyroid, breast, stomach, and prostate." (PMID 35205705, 2022). "Further, the risk of thyroid cancers in the CHEK2 carriers was only 1.5% over ten years." (PMID 35205705, 2022). "Their analysis of 4008 cases with 13 tumor types and 4000 controls found a moderately increased risk of breast, prostate, and thyroid cancer in carriers of truncating CHEK2 mutations and an increased risk of breast, colon, kidney, prostate, and thyroid cancer for the carriers of p.I157T." (PMID 33322746, 2020). "We speculate that SMARCB1 is an important effector in addition to NF2 and CHEK2 inactivation among thyroid cancers with chromosome 22q loss." (PMID 32380731, 2020). "Thus, the tumor spectrum in patients with pathogenic CHEK2 variants seems to include thyroid cancer and appears to be broader than previously thought." (PMID 30680046, 2019). "Among 507 females with BC and thyroid cancer, CHEK2 PVs (n = 22, 4.3%, 95% CI 2.9–6.5%) were detected most frequently." (PMID 36856935, 2023). "Two genes were identified to be connected with coexisting breast and thyroid cancer: CHEK2 and PARP4." (PMID 37434214, 2023).
thyroid cancer (continued). "In the family #3, the index had had thyroid cancer preceding MM and carried P variants in POT1, CHEK2, and MUTYH but the father with MM (#3_I.1) shared only the CHEK2 and MUTYH variants." (PMID 36467798, 2022). "Only the guidelines of the International Hereditary Cancer Centre propose screening for thyroid cancer in CHEK2 carriers, based on the Polish case-control studies." (PMID 35101071, 2022). "CHEK2 PVs were frequent in females with BC who also had either thyroid cancer or kidney cancer." (PMID 36856935, 2023). "Current national and most international guidelines do not recommend screening for thyroid cancer in patients with CHEK2 mutations." (PMID 35101071, 2022). "There are no data available on thyroid specific mortality in CHEK2 mutation carriers, nor is it clear if thyroid cancer in this population is more aggressive or presents at an earlier age." (PMID 35101071, 2022). "There is a low level of evidence for a slightly higher incidence of thyroid cancer in patients with (likely) pathogenic CHEK2 mutations compared to non-carriers." (PMID 35101071, 2022). "The ten-year risk of developing thyroid cancer was higher in women who carried a CHEK2 mutation (1.5%) than in women who carried no mutation (0.9%)." (PMID 35205705, 2022). "The ten-year risk of thyroid cancer was higher in women who carried a CHEK2 mutation (1.5%) than in women who carried no mutation (0.9%)." (PMID 35205705, 2022). "Notably, four gene-disease associations, namely, ATM-gastric cancer, CHEK2-gastric cancer, CHEK2-kidney cancer, and CHEK2-thyroid cancer, were verified by NLP literature review alone." (PMID 33959510, 2021). "Of note, four gene-disease associations, i.e., ATM-gastric cancer, CHEK2-gastric cancer, CHEK2-kidney cancer, and CHEK2-thyroid cancer, were not identified in any of the six resources but were verified by the NLP-aided literature review." (PMID 33959510, 2021). "Despite the high probability of an association with several other cancers, including renal and thyroid cancer, there is no recommendation to prevent these tumors in CHEK2 carriers." (PMID 33322746, 2020). "Four of the five patients from group U with a truncating CHEK2 mutation had thyroid cancer (in group K only one patient carried a truncating CHEK2 mutation, no thyroid cancer is reported)." (PMID 30680046, 2019). "In addition, NGS analysis of the thyroid cancer (PTC) from patient II.4 from family F83 showed that there were no somatic CHEK2 variants." (PMID 38367672, 2024). "The specific CHEK2 variants in thyroid cancer cases were not reported." (PMID 35101071, 2022). "Among the selected genes in the 22q area, CHEK2, LIMK2, and TIMP3 have already been reported to be deleted/down-regulated in thyroid cancer; the 22q deletion may play a role in thyroid carcinogenesis." (PMID 22558328, 2012). "A significant excess of malignant neoplasm of thyroid and other endocrine tumors (C73-C75) was observed in MyCode but not UKBB; this was almost entirely driven by thyroid tumors (C73) and, unlike most other associations, by CHEK2 PMV." (PMID 41396600, 2025). "CHEK2 and EWSR1 both converge in the DNA-damage repair pathway, therefore we hypothesized that in this family they might act in combination for the development of thyroid cancer." (PMID 33946592, 2021). "Additionally, given the roles of CHEK2 and APC in key cellular pathways, targeted therapies that aim to restore normal function in these pathways could hold promise for the management of secondary thyroid cancer in childhood cancer survivors." (PMID 39860595, 2025).
pancreatic cancer (47 papers, 2009 to 2026). "Among these patients, EOCRC#09 (CHEK2 variant) had a maternal family history of breast and pancreatic cancer (2nd- and 3rd-degree relatives)." (PMID 40429818, 2025). "We also identified CHEK2 P/LP variants in two patients (0.27%); both had intestinal GC at 55 years and 64 years and a family history of breast, prostate, and pancreatic cancer." (PMID 40446793, 2025). "Two women (14.3%) have P/LP variants in the CHEK2 gene, and their relatives have breast and pancreas cancer." (PMID 38890714, 2024). "PTVs in ATM and CHEK2 are associated with a wide range of cancers, with the highest RR for pancreatic cancer in ATM PTV carriers." (PMID 39209703, 2024). "Based on a review of the evidence in the literature there are some studies that examine the impact of CHEK2 mutations on patient survival who have been diagnosed with breast, prostate or pancreatic cancer." (PMID 34499690, 2021). "An association with pancreatic cancer is less evident, but mutations in genes coding for DDR proteins (including CHEK2) in pancreatic cancer patients were associated with improved survival." (PMID 33322746, 2020). "However, another tumor-agnostic phase 2 study showed no significant anticancer activity of olaparib in somatic or germline ATM- or CHEK2-mutated cancers, although only four patients with pancreatic cancer were enrolled." (PMID 39456541, 2024). "Indeed, not only a genomics approach has associated the olfactory transduction pathway with an increased pancreas cancer risk but moreover overexpression of 34 ORs genes has been reported in patients bearing breast tumors caused by CHEK2 1100delC-mutation." (PMID 24416348, 2014). "Patient 3 presented with bilateral BC at 47, her mother died from pancreas cancer, her maternal grandmother had CRC, her paternal grandmother had BC; she had the MUTYH c.536A>G (p.Tyr179cys), but also a mutation in CHEK2: c.470T>C (p.Ile157Thr) that is known as pathogenic." (PMID 41001951, 2025). "Most familial pancreatic cancer is attributable to hereditary breast and ovarian cancer syndrome that results from germline mutations in BRCA1/2 genes and other genes such as ATM, BRIP1, CHEK2, RAD50, and RAD51C." (PMID 38732320, 2024). "For CHEK2, a two-fold association has been reported for patients with familial pancreatic cancer in a recent study from Poland, but the association was not seen in unselected PDAC patients or individuals in familial pancreatic cancer families who did not have cancer." (PMID 35805029, 2022). "MGPTs generally cover at least 10 common HR-related genes such as ATM, BARD1, BRCA1, BRCA2, BRIP1, CHEK2, NBS1 (NBN), PALB2, RAD51C, and RAD51D, all of whose germline alterations are associated with BRCAness phenotypes for predisposition to breast, ovarian, prostate, or pancreatic cancer." (PMID 35008774, 2021). "In a case series on pancreatic ductal adenocarcinoma, 8 out of 10 pancreatic cancer patients with ATM, ATR, or CHEK2 GPVs were treated with an oxaliplatin-based chemotherapy regimen and 5 patients demonstrated a partial response or stable disease." (PMID 35806485, 2022). "Of the 6474 patients with pancreatic cancer, 27 (0.4%) had BRCA1 alterations, 108 (1.7%) had BRCA2 alterations, 76 (1.2%) had germline ATM alterations, 25 (0.4%) had PALB2 alterations, and 27 (0.4%) had CHEK2 alterations." (PMID 40361359, 2025). "In line with this, although ATM and CHEK2 mutations have been suggested to associate with increased response to DNA-damaging therapy, a recent analysis showed that ATM and CHEK2 mutant pancreatic cancer does not show evidence of HRD by multiple genetic HR classifiers." (PMID 34572943, 2021).